CTSV (cathepsin V)
Diseases named in the same sentence as CTSV in open-access papers (continued):
Sharing a sentence is not in itself a finding about the gene and the disease.
cancer (29 papers, 2012 to 2025). A tumor composed of atypical neoplastic, often pleomorphic cells that invade other tissues. "Taken together, these results indicate that cathepsin V could be used as a diagnostic and prognostic marker for cancer." (PMID 36147668, 2022). "Elevated cathepsin V levels have been associated with various pathological processes, including myasthenia gravis, atherosclerosis, vascular inflammation, type 1 diabetes, mucopolysaccharidoses, neurological diseases, and cancer." (PMID 36147668, 2022). "CTSV was significantly upregulated in cancer tissue compared to adjacent normal tissue, with elevated CTSV expression correlating with adverse clinicopathological features and poor prognosis in HCC." (PMID 40269756, 2025). "With the aid of the TCGA database, we carried out a pan-cancer analysis to look into CTSV expression in tumors." (PMID 38078882, 2023). "Further exploration of the Kaplan-Meier Plotter database showed that elevated CTSV expression was correlated with poor survival in cancer patients." (PMID 35494076, 2022). "Further, we demonstrate that cathepsin V is a potential target for new approaches to cancer therapy." (PMID 36147668, 2022). "Praeruptorin B was found to potently inhibit migration and invasion of the RCC cells, as evidenced by decreased production of cathepsin C (CTSC) and cathepsin V (CTSV) proteins, proteases that regulate cancer cell invasion extracellularly." (PMID 35805049, 2022). "CTSV is also crucial for cancer cell viability and proliferation since it triggers the inflammatory pathway." (PMID 35443863, 2022). "While detecting the protein expression of CTSV in cancer cell lines, we noticed that the CTSV detection by Western blotting revealed more than one band, and the majority of the protein was found at 43 kDa." (PMID 35494076, 2022). "As NK cells and CTLs are the main effector cells in the antitumor immune response, selective cathepsin V inhibitors are candidates to be included in protocols of cancer immunotherapy." (PMID 36147668, 2022). "Our results therefore confirm that cathepsin V is a potential target for improving cancer therapy and provide lead compounds for further development and optimization." (PMID 36147668, 2022). "CTSV is one of 16 cancer related genes on the Oncotype DX® array which is used to assess the risk of ER-positive breast cancer recurrence and to determine the benefits of adjuvant chemotherapy treatment." (PMID 33298139, 2020). "The function of cathepsin V in triggering hyperproliferation is possibly explained by specific forms reaching the nucleus of carcinoma cells." (PMID 33266306, 2020). "It is noteworthy that cathepsin V was also expressed in PDLCs, non-cancer cell lines isolated from healthy teeth, at a high level." (PMID 30602733, 2019). "However, the nuclear localisation of CtsV has been reported in the case of thyroid carcinoma cells, contributing to the increased proliferation of cancer cells, specifically accumulating in the nuclei of these cells during the S phase." (PMID 39851495, 2025). "To now, no adequate research has been carried out to investigate the function of CTSV in cancer." (PMID 35443863, 2022). "Due to its role in cancer progression, cathepsin V is considered a target for antitumor treatment." (PMID 36147668, 2022). "Cathepsins have diverse roles in cancer biology and cathepsin V promotes cancer cell invasion." (PMID 29861857, 2018). "Notably, only one cytokine; CTSV was highly secreted by cancer cells only." (PMID 40411295, 2025). "Among those, Cathepsin V (CTSV) (log2FC = 7.2, P = 0.002), a protease involved in ECM degradation, was secreted exclusively by cancer cells." (PMID 40411295, 2025). "Similarly, CtsV extracellularly targets E-cadherin, but also JAM-2, thus contributing to EMT in cancer cells." (PMID 39851495, 2025).
cancer (continued). "In clear contrast, full-length cathepsin V was not sorted to the nucleus but was detected in the compartments of the secretory pathway of thyroid epithelial and carcinoma cells consistent with the existence of an N-terminal signal peptide." (PMID 33266306, 2020).
benign tumors (1 paper, 2020). "A six-biomarker model including HE4, CA125, CEACAM1, CTSV, CXCL6, S100A4 and age was found to be the best model for discriminating between benign tumors and EOC with AUC 0.921 (0.863–0.979), sensitivity 0.897 / specificity 0.889 at best point cut-off (p = 0.025)." (PMID 33075095, 2020).
neurological diseases (1 paper, 2022). "Cathepsin V has been proposed as a promising therapeutic target because of its restricted expression under physiological conditions and specific functions during pathological processes in cancerous, cardiovascular, and neurological diseases." (PMID 36147668, 2022).
CTSV also shares sentences with these, for which no sentence is quoted: squamous cell carcinoma (3 papers); cervical carcinoma (2); infection (2); lung adenocarcinoma (2); malignant melanoma (2); renal carcinoma (2); Allergy (1); Arrhythmia (1); asthma (1); astrocytoma (1); atrial fibrillation (1); cholangiocarcinoma (1); colon carcinoma (1); Diabetes (1); digestive system tumors (1); hematological disease (1); immune disorders (1); metastatic carcinoma (1); metastatic tumors (1); muscular atrophy (1); Myocardial fibrosis (1); oral disease (1); osteoarthritis (1); ovarian carcinoma (1); skin cancer (1).